PDE2A (phosphodiesterase 2A)
Diseases named in the same sentence as PDE2A in open-access papers (continued):
Sharing a sentence is not in itself a finding about the gene and the disease.
radiculitis (1 paper, 2018). An inflammatory process affecting a nerve root. "Intrathecal administration of low-concentration oxygen/ozone alleviated mechanical allodynia and attenuated radiculitis, likely by a PDE2A-cGMP/cAMP-NF-κB/p65 signaling pathway in chronic radiculitis rats." (PMID 30651902, 2018). "Moreover, intrathecal administration of 20 μg/mL oxygen/ozone reversed the increased levels of spinal PDE2A and NF-κB/p65 mRNA and protein expressions in rats with chronic radiculitis." (PMID 30651902, 2018). "Therefore, we inferred that low-concentration O3 decreased the overexpression of spinal PDE2A, which lessens the hydrolysis of cAMP and cGMP, which leads to alleviation of radiculitis and mechanical allodynia." (PMID 30651902, 2018). "We believe that radiculitis and mechanical allodynia might be attributed to the PDE2A-cAMP/cGMP-NF-κB/p65 signaling pathway in chronic radiculitis rats and that low-concentration O3 attenuates radiculitis and mechanical allodynia by altering this signaling pathway." (PMID 30651902, 2018).
retinoblastoma (1 paper, 2024). A malignant tumor that originates in the nuclear layer of the retina. "In retinoblastoma (RB), PDE2A showed positive correlations with differentiation, angiogenesis, and inflammation." (PMID 39699377, 2024).
Sepsis (1 paper, 2016). Sepsis is defined as life-threatening organ dysfunction caused by a dysregulated host response to infection. "Pretreatment with PDE2A inhibitor in vivo partially improved sepsis-induced myocardial dysfunction in mice." (PMID 27973394, 2016).
stress-related disorder (1 paper, 2025). Stress-related disorders are mental health disorders that are a result of an atypical response to both short and long-term anxiety due to physical, mental, or emotional stress. "One notable finding was an increase in phosphodiesterase 2A (PDE2A) whose inhibition was shown to attenuate AUD induced by stress-related disorders suggesting that binge drinking during fear-conditioning could create vulnerabilities for future chronic drinking." (PMID 40560842, 2025).
thymoma (1 paper, 2024). A neoplasm arising from the epithelial cells of the thymus. "Conversely, in thymoma (THYM) tissues, PDE2A levels were significantly elevated compared to normal tissues (P<0.05)." (PMID 39699377, 2024).
uveal melanoma (1 paper, 2024). A melanoma derived from melanocytes of the uveal tract. "In uveal melanoma (UM), PDE2A was negatively correlated with differentiation and inflammation." (PMID 39699377, 2024). "However, highly expressed PDE2A group was related to poor prognosis in BLCA (P=0.034), LUSC (P=0.019), OV (P=0.011), STAD (P=0.0096), and uveal melanoma (UVM) (P=0.01)." (PMID 39699377, 2024).
viral infection (1 paper, 2010). "Finally, both PDE2A (MIM 602658) and SCNN1A (MIM 600228) might play a role in maintaining lung epithelial barrier homoeostasis during viral infection." (PMID 20174570, 2010).
cancer (12 papers, 2016 to 2025). A tumor composed of atypical neoplastic, often pleomorphic cells that invade other tissues. "Future studies should focus on elucidating the molecular mechanisms underlying PDE2A's functions in cancer, validating these findings in larger cohorts, and exploring its potential as a therapeutic target in preclinical and clinical settings." (PMID 39699377, 2024). "Genetic alteration analysis provided insights into the mutational landscape of PDE2A across different cancers." (PMID 39699377, 2024). "The identification of SEMA6B, RUNDC3B, MICU3, and KCNK3 as top PDE2A-correlated genes provided novel targets for functional validation studies aimed at elucidating the molecular mechanisms underlying PDE2A's role in cancer." (PMID 39699377, 2024). "Our findings revealed a predominantly positive association between PDE2A and key cancer functions such as angiogenesis, differentiation, metastasis, quiescence, and stemness." (PMID 39699377, 2024). "A high expression in distinct brain areas as well as in cancer cells makes PDE2A an interesting therapeutic and diagnostic target for neurodegenerative and neuropsychiatric diseases as well as for cancer." (PMID 36297384, 2022). "While genes such as PTH1R, DPT, DES, TCF21 and PDE2A are downregulated in many cancers, cell cycle associated genes, centromere proteins and kinesin family proteins are upregulated in all the cancer types we studied." (PMID 34728699, 2021). "CSPP1 is a mitosis regulator; LGALS7 and PDE2A are overexpressed in different cancer types; LDHA encodes one of the major glycolysis enzymes." (PMID 27359056, 2016). "Recent studies have shown that PDE2A is associated with some tumors, but its expression profiles, prognostic significance, and immunological roles in diverse cancer types remain unclear." (PMID 39699377, 2024). "Furthermore, PDE2A expression in most cancers was positively associated with PDCD1, EDNRB, ADORA2A, TGFB1, and especially C10orf54." (PMID 39699377, 2024). "In this comprehensive pan-cancer analysis, we have systematically explored the expression patterns, clinicopathological correlations, prognostic value, genetic and epigenetic alterations, immune cell infiltration, and drug sensitivity associated with the PDE2A gene across multiple human cancers." (PMID 39699377, 2024). "Utilizing advanced bioinformatics tools, we performed a comprehensive analysis of PDE2A gene expression in multiple human cancers." (PMID 39699377, 2024). "We employed the GEPIA2.0 tool to assess the prognostic significance of PDE2A expression in cancer patients." (PMID 39699377, 2024). "Utilizing data from the TCGA project, we constructed a comprehensive overview of PDE2A expression across various human cancers." (PMID 39699377, 2024). "The single-cell level analysis of PDE2A expression offered insights into its functional state in different cancers." (PMID 39699377, 2024). "We observed a significant downregulation of PDE2A expression in most types of cancers and across various pathological stages of tumorigenesis, suggesting a potential tumor suppressor role for PDE2A." (PMID 39699377, 2024). "Our comprehensive pan-cancer analysis of PDE2A revealed its multifaceted roles in tumorigenesis, progression, and immunological roles across multiple cancer types." (PMID 39699377, 2024). "Our study revealed that PDE2A expression was significantly reduced in the majority of cancer types and clinicopathological stages (I to IV) compared to normal tissues." (PMID 39699377, 2024). "Single cell sequencing revealed PDE2A's crucial role in regulating differentiation and angiogenesis of cancer cells." (PMID 39699377, 2024). "The correlation heatmap showed that PDE2A was positively associated with SEMA6B, RUNDC3B, MICU3, and KCNK3 genes in the majority of cancers." (PMID 39699377, 2024). "The observed decline in PDE2A methylation levels in most cancers suggested epigenetic deregulation as a potential mechanism underlying its altered expression." (PMID 39699377, 2024).
cancer (continued). "Cox regression analyses indicated that PDE2A can act as an independent prognostic factor for these cancers." (PMID 39699377, 2024). "Our findings revealed intricate and diverse roles played by PDE2A in tumorigenesis and cancer progression, highlighting its potential as a therapeutic target and prognostic marker in specific cancer types." (PMID 39699377, 2024). "This research provided a comprehensive analysis of PDE2A in human cancers, highlighting its potential as both a prognostic marker and an immunotherapy target for future research." (PMID 39699377, 2024). "To unravel the biological functional state of PDE2A at the single-cell level in different cancers, we utilized CancerSEA tool." (PMID 39699377, 2024). "PDE2A expression levels of tumor tissues were significantly lower than the corresponding normal tissues in 25 of 27 cancer types." (PMID 36611861, 2022). "Since PDE2A plays an important role in regulating cAMP/cGMP levels and mitochondrial functions, which are closely related to tumor progression, we analyzed the mRNA expression of PDE2A in TCGA pan-cancer datasets." (PMID 36611861, 2022). "Because our analysis suggested that our predictive model distinguished the patients with high and low EMT signatures, we further explored the role of PDE2A in cancer cell invasion and EMT." (PMID 36054420, 2022). "Our previous study and other reports have suggested that both miR-139 and its host gene PDE2A are putative antitumor genes in various cancers." (PMID 34512162, 2021). "Considering that the autocrine of Wnt signaling is one of characteristics of cancer stemness, the secretion of Wnt ligands was determined after miR-139/PDE2A overexpression." (PMID 34512162, 2021). "To further reveal the molecular mechanism of how LINC01537 regulates cancer development, we tentatively verified that the lncRNA can increase PDE2A expression by RNA–RNA interaction." (PMID 31374807, 2019). "Our findings suggest that TQ modulates Wnt signaling by altering the expression of its core components (WNT7B and WNT6) and regulators (PDE2A and Sema3C), thereby potentially downregulating this oncogenic pathway and contributing to its anti-cancer mechanism in vitro." (PMID 39874307, 2025). "This enabled us to analyze the correlation between PDE2A and functional status of various cancers." (PMID 39699377, 2024). "Our research indicated a potential interaction between PDE2A and PD-1, positioning PDE2A as a pivotal mediator that could impact cancer prognosis and tumor immunity." (PMID 39699377, 2024). "Our findings may provide novel insights into the complex roles of PDE2A in cancer biology and highlight its potential as a prognostic and immunotherapeutic target in multiple cancer types." (PMID 39699377, 2024). "As PDE2A was negatively correlated with tumor growth status, vascular infiltration, and promoted the HCC progression, and metastasis is one of the leading causes of cancer death." (PMID 38568089, 2024). "The expression of PDE2A was down-regulated in various cancer types including HCC." (PMID 38568089, 2024). "These epigenetic modifications could represent promising therapeutic targets for reversing abnormal PDE2A expression in cancers." (PMID 39699377, 2024). "However, the observed decline in PDE2A methylation levels in most cancers suggested the existence of a more complex mechanism for gene expression regulation." (PMID 39699377, 2024). "Therefore, it is necessary to explore the expression patterns and functional roles of PDE2A in different cancer types to gain a comprehensive understanding of its involvement in tumorigenesis and progression." (PMID 39699377, 2024). "In order to investigate the correlation between PDE2A expression and clinical pathological characteristics, we employed the UALCAN platform to analyze the variations in PDE2A expression across normal tissues and tumor tissues at different stages of cancer development." (PMID 39699377, 2024).
cancer (continued). "The level of PDE2A DNA methylation was significantly decreased in most cancers." (PMID 39699377, 2024). "The involvement of synaptic transmission and synaptic vesicle cycle pathways suggested a potential role for PDE2A in neuronal signaling processes that might be dysregulated in cancers originating from or metastasizing to the nervous system." (PMID 39699377, 2024). "In the present study, we first analyzed the expression levels of PDE2A in pan-cancer and showed that it was significantly downregulated in the vast majority of tumor tissues compared to non-tumor tissues, including HCC, except for two immune system tumors, DLBC and THYM." (PMID 36611861, 2022). "Importantly, a high expression of PDE2A has been detected in cancer cells, e.g., in squamous carcinoma HeLa cells and oral osteosarcoma HOSM-1 cells along with cytotoxic and pro-apoptotic effects of pharmacological inhibition of PDEs." (PMID 36297384, 2022). "In addition, we examined the relationship between PDE2A and functional states in specific cancers." (PMID 39699377, 2024). "The positive correlations observed between PDE2A and most ICP genes in several cancers suggest a role in enhancing antitumor immunity, while the negative correlations in LGG indicate a possible immunosuppressive function in this specific tumor type." (PMID 39699377, 2024). "In most cancers, the signature genes were differentially methylated compared to normal tissue; in particular, genes including as representatives NCOA4, CTSL, MCUB, ANXA5 and ANGPTL2 were usually hypermethylated, while genes including PDE2A and others were usually hypomethylated." (PMID 37660060, 2023). "However, the exact role of PDE2A in cancer has not yet been fully elucidated." (PMID 39699377, 2024).
tumor (9 papers, 2013 to 2024). "Given that immune cell infiltration is tightly connected to tumor establishment and progression, we explored the association of PDE2A with immune cell infiltration across 44 tumors by quanTIseq algorithm." (PMID 39699377, 2024). "Significant associations were observed between PDE2A expression and tumor mutation burden as well as microsatellite instability." (PMID 39699377, 2024). "The results of KEGG pathway analysis revealed that synaptic vesicle cycle was predominately associated with the effects of PDE2A on tumor development." (PMID 39699377, 2024). "Besides, based on functional annotation of PDE2A-associated DEGs, PDE2A was closely associated with tumor metastasis pathways, including ECM organization, tumor progression pathways, such as ERK1 and ERK2 cascade, and digestive system development." (PMID 36611861, 2022). "Functional enrichment analysis emphasized the important role of PDE2A in synaptic transmission and tumor development." (PMID 39699377, 2024). "PDE2A was negatively correlated with tumor growth status, vascular infiltration, and promoted the HCC progression through modulating mitochondrial morphology and ATP content as well influencing cell cycle of HCC." (PMID 38568089, 2024). "Although PDE2A shows promise as a tumor marker with potential clinical applications, there is still a considerable distance to traverse before it can be effectively applied in clinical practice." (PMID 39699377, 2024). "The IHC results showed that PDE2A is highly expressed in non-tumor tissues and decreases with the T stage." (PMID 36611861, 2022). "Phosphodiesterase 2 (PDE2A) modulates the levels of cAMP/cGMP and was recently found to be involved in mitochondria function regulation, closely related to multiple types of tumor progression." (PMID 36611861, 2022). "Lower PDE2A expression was a protective factor in HCC and was negatively associated with serum AFP levels, tumor status, vascular invasion, histologic grade, and pathologic stage of HCC." (PMID 36611861, 2022). "Furthermore, leveraging the CPTAC datasets, we investigated the differences in PDE2A protein expression between tumor and corresponding normal tissues." (PMID 39699377, 2024). "Furthermore, tumor infiltration levels of M2 macrophages and Treg cells exhibit a significant positive correlation with the expression levels of PDE2A in several types of tumors, including STAD, OV, and COAD." (PMID 39699377, 2024). "Non-invasive imaging of potential drug targets and biomarkers such as PDE2A by means of PET may help in analysing the relationship between PDE2A protein level and tumor biology and is suggested to increase the success rate in PDE2A targeted drug discovery." (PMID 36297384, 2022). "Therefore, low PDE2A expression in HCC seemed to impair anti-tumor immune responses, promote the escape of tumors from elimination, and finally accelerate tumorigenesis." (PMID 36611861, 2022). "We wanted to understand if PDE2A was a major effector of LINC01537-mediated tumor suppression." (PMID 31374807, 2019). "PDE2 activity and PDE2A mRNA expression in normal and malignant tumor cells have been reported." (PMID 23381931, 2013). "Notably, PDE2A expression was positively correlated with PDCD1 in most tumor tissues." (PMID 39699377, 2024). "The differential prognostic outcomes based on PDE2A expression levels may be attributed to multiple factors, including specific tumor types, tumor heterogeneity, epigenetic modifications, complex gene-gene interactions, tumor microenvironment, and other factors." (PMID 39699377, 2024). "Similarly, in OV, low expression of PDE2A may be more inclined to inhibit the infiltration of Treg and M2 macrophages, resulting in a favorable tumor prognosis." (PMID 39699377, 2024). "Therefore, we propose that LINC01537/PDE2A might repress the development of digestive gland malignancies as well, such as tumor proliferation, invasion and metastasis." (PMID 36054420, 2022).
tumor (continued). "Moreover, the 5-year Decision Curve Analysis (DCA) showed that PDE2A, combined with tumor status, pathological stage, M stage, and T stage could predict well the prognosis and survival of HCC patients." (PMID 36611861, 2022). "Therefore, PDE2A may play a pivotal role in tumor-immune interactions." (PMID 39699377, 2024). "However, the mechanism of PDE2A on tumor progression and prognosis remains unclear." (PMID 36611861, 2022). "Although the methylation level of the PDE2A gene was relatively low in tumor tissues, this did not always imply an increase in gene expression." (PMID 39699377, 2024). "Additionally, in LGG, the expression level of PDE2A shows a significant negative correlation with the tumor infiltration level of M2 macrophages." (PMID 39699377, 2024). "The protective role of PDE2A was also observed in high PDE2A expression HCC patients with no vascular invasion, tumor-free status, and low serum AFP levels." (PMID 36611861, 2022). "Since PDE2A plays a pivotal role in energy metabolism, there can be no doubt that LINC01537 exerted an effect on tumor energy metabolism." (PMID 31374807, 2019).
neurodegenerative disease (4 papers, 2019 to 2025). A disorder of the central nervous system characterized by gradual and progressive loss of neural tissue and neurologic function. "This enzymatic activity is essential for neuronal function, and PDE2A has emerged as a molecular target for neuroimaging in neuropsychiatric disorders and neurodegenerative diseases." (PMID 41531954, 2025). "Starting with the PDE2A enzyme, the radioligand [18F]4 ([18F]PF-05270430) has been further evaluated to confirm its suitability for target occupancy examinations in the assessment of novel PDE2A inhibitors as therapeutics for neuropsychiatric and neurodegenerative diseases." (PMID 33917199, 2021). "In addition to PDE2A, another protein that was increased at 3 and 24 weeks post injury was tau tubulin kinase 1 (TTBK1), which is known to be linked to the development of several neurodegenerative diseases such as ALS, FTLD, and AD." (PMID 35850691, 2022).
neurological disorders (2 papers, 2015 to 2022). "Phosphodiesterase 2A (PDE2A) is highly and specifically expressed in particular brain regions that are affected by neurological disorders and in certain tumors." (PMID 26016549, 2015). "Besides further PDE2A inhibitors developed for treatment of neurological disorders, two PDE2A radioligands for molecular imaging of this protein in the brain via positron emission tomography (PET) have been reported to date." (PMID 26016549, 2015).
genetic disorders (1 paper, 2022). "We collected and reviewed 74 articles (17 for GNB1, 46 for GNAO1, 6 for PDE10A, 2 for PDE2A, and 3 for HCPCA) describing motor, epileptic, and developmental phenotype of patients with genetic disorders of GPCRs–cAMP signaling pathway." (PMID 36003298, 2022).
heart diseases (1 paper, 2024). "Overall, PDE2A plays a pathophysiological role in heart diseases; inhibition of PDE2 in cardiomyocytes might be beneficial to counteract pathological remodeling induced by pressure overload." (PMID 37971403, 2024).